CD4 (CD4 molecule)
Diseases named in the same sentence as CD4 in open-access papers (continued):
Sharing a sentence is not in itself a finding about the gene and the disease.
tumor (continued). "However, where and how naïve cancer cell-specific CD4 T cells get activated in a tumor setting is less clear." (PMID 31143179, 2019). "Therefore, we developed positron emission tomography (PET) radiotracers for non-invasive detection of CD4+ and CD8a+ TILs in syngeneic mouse tumor models for preclinical studies." (PMID 31754392, 2019). "While CD8+, CD4+ Th1 and NK cells are generally considered to favor a tumor-suppressive response, CD4+ T-helper 2 (Th2), FOXP3+ T-regulatory and dendritic cells might play a pro-tumorigenic role." (PMID 30922362, 2019). "CD4 + staining was inconclusive due to high background expression of CD4 in EL4 tumor cells." (PMID 30820474, 2019). "Interestingly, the cell viability of B16F10 cells was significantly lower than that in tumor-bearing CD4+ T cells when cryo-thermal-CD4+ T cells were cultured with B16F10 cells at ratios of 1:1 and 2:1." (PMID 30833570, 2019). "CD4+ Th1 and Th2 cells exert cytotoxic effects on tumor cells by secreting IL-2, IL-4, and IFN-γ." (PMID 31443339, 2019). "Tregs, a population characterized by FoxP3+ CD25+ CD4+ T cells, significantly suppress immune responses, and it has been shown that their depletion effectively eradicates tumor cells via an enhanced anti-tumor immune response." (PMID 31192215, 2019). "Interestingly, we observed changes in the leukocyte tumor microenvironment in favor of CD8+ cells in proportion to CD4+ T cells and regulatory T cells (Tregs)." (PMID 31046839, 2019). "If this will be confirmed in future studies, tumors cells expressing MHC class II molecules not only act as APC for priming naïve tumor-specific CD4+ T cells but also perform APC activity ectopically with respect to the canonical site represented by the lymph nodes." (PMID 31417570, 2019). "Similarly, patients with a low infiltration of the tumor with CD4+ T cells had a significantly worse overall survival compared with those with high CD4+ infiltration (P =0.05)." (PMID 31429521, 2019). "The tumour-bearing CD4+ T cells co-cultured with tumor-bearing eosinophils was as the control." (PMID 31519961, 2019). "Tumor responses occurred in HIV patients with low CD4 T-cell counts." (PMID 31847881, 2019). "In addition to the T cell differentiation state, the presence of CD4+ T cells in infused cell products is important for effective tumor cell killing by CD8+ T cells." (PMID 31565660, 2019). "HHLA2 overexpression was associated with sparser CD3+ tumor infiltrating lymphocytes (TILs), CD8+ TILs and a higher CD4 + Foxp3+/CD8+ TIL ratio, whereas PD-L1 expression was associated with prominent T cells and CD163+ tumor associated macrophages infiltrations." (PMID 30885276, 2019). "However, other studies found that low IL-1β concentrations promote CD4+ T cells to secrete IL-17, inhibiting the body’s anti-tumor effects, while high IL-1β concentrations activate CD8+ T cells and promote anti-tumor effects." (PMID 31754923, 2019). "In B16-F10 tumors that were irradiated with 2 × 5Gy and vaccinated once with HHP-killed tumor cells, the amount of natural killer (NK) cells, monocytes/macrophages, CD4+ T cells and NKT cells was significantly increased, while the amount of B cells was significantly decreased." (PMID 31555582, 2019). "Our results demonstrate that the combined treatment with low-dose HMGN1 and anti-CD4 depleting antibody exerts synergistic anti-tumor effects by promoting CD8+ T cell activation, expansion, and by counteracting exhaustion of activated CD8+ T cells in the tumor." (PMID 30696484, 2019). "In addition, CD4+ T cells also orchestrated dendritic cells (DCs) to activate CD8+ T cells either by cross-presenting tumor antigens to CD8+ T cells or by inducing the production of IL-2." (PMID 30913212, 2019).
tumor (continued). "Considering the effect of smoking on tumor immunity, we attempted to investigate the impact of smoking history on the prognostic value of circulating naïve and memory CD4+ and CD8+ T cells in advanced non-small cell lung cancer (NSCLC) treated with chemo(radio)therapy." (PMID 31320838, 2019). "Although all patients died due to progressive disease, neoantigen-specific CD8+ and CD4+ T cells could be observed which were able to infiltrate into the tumor." (PMID 31040852, 2019). "CD4+ and CD8+ T cells act synergistically to cause tumor regression." (PMID 31112530, 2019). "However, TNFα‐CSG treatment and adoptive transfer of both CD8+ and CD4+ T cells (triple combination) produced anti‐tumour effects similar to those observed in syngeneic 4T1 tumour‐bearing mice." (PMID 31709774, 2019). "In similar results from our previous study, we demonstrated that BACH2 could play a role as a tumor suppressor gene by increasing the apoptosis of CD4+ T-cells in vitro." (PMID 30654767, 2019). "Furthermore, the ratio of neutrophils/T lymphocytes per gram of tumor (approximated using the sum of CD45+CD4+ cells and CD45+CD8+ cells) was also lower in the tumors from mice treated with the combination of TAB004 + Lip-MSA-IL-2." (PMID 31114758, 2019). "The prognostic value of a high CD4:CD8 ratio among tumor-infiltrating T cells remains unclear, as it has been associated with both better and worse survival in different studies." (PMID 31261914, 2019). "However, it is interesting to note that the depletion of CD4 T cells can eliminate this therapeutic effect, presenting a previously unappreciated link between TAMs and CD4 T helper cells, as well as tumor death." (PMID 29867979, 2018). "However, the compromised effect of CD4+ T cells or NK cells depletion was less important than CD8+ T cells in Notch1-mediated tumor growth." (PMID 29301578, 2018). "Furthermore, the using of whole tumor cell lysate represents a rich source of antigens with epitopes for CD8+ cytotoxic T cells (CTLs) as well as CD4+ T helper cells that generate strong and a long-lasting antitumor immune response." (PMID 30081891, 2018). "As Luciferase-DBY is a cytoplasmic Ag, we checked whether increasing availability of DBY at the tumor site would improve the CD4+ T cell response." (PMID 29844317, 2018). "In pre-treated tumor-bearing rats, only CD4 Tem cells were elevated above naïve controls." (PMID 29533981, 2018). "We also performed CD4 depletion on EMT6 tumor-bearing mice to determine whether CD4+ T cells contributed to the anti-tumor efficacy of M7824." (PMID 29721396, 2018). "Combined therapy enhances tumor infiltration by CD4+, CD8+ lymphocytes and NK cells." (PMID 29320562, 2018). "It has been strongly suggested that antigen-specific CD4+ Tregs at tumor sites may significantly suppress immune responses, leading to immune tolerance of tumor cells." (PMID 28669079, 2018). "Tumor outgrowth is mainly controlled by CD4 and CD8 T cells." (PMID 29032503, 2018). "The authors demonstrated increased levels of PD-L1 expression, increased amounts of circulating CD8+ and CD4+ T cells, and increased inflammation at tumor sites distant from the injected lesions (even in patients with low levels of tumor infiltrating lymphocytes [TIL])." (PMID 30426287, 2018). "To ascertain if the molecular changes took place in cancer cells or in the infiltrating immune cells, we performed experiments using tumor cell suspensions depleted of the main infiltrating immune cell subsets, namely CD4+ and CD8+ T lymphocytes and macrophages." (PMID 29971064, 2018). "Tumor-derived CD4+ Treg cells have been extensively studied in many different types of cancer." (PMID 28669079, 2018). "Finally, we found a decreased methylation of the IL17A locus in CD4+ T cells in the tumour compared to PBMCs (p < 0.01)." (PMID 30075815, 2018).
tumor (continued). "In addition, an increase in tumor-infiltration of CD4+IFNγ+ T cells (p < 0.05) and CD8+ IFNγ+ T cells (p = 0.057) was detected in the H + anti-PD-1 combination therapy." (PMID 30333031, 2018). "Interestingly, the ratio of CD8+ T versus CD4+ T cells in the tumor was higher than in the spleen, implying that the HCC TME preferentially attracted CD8+ T cells but suppressed their effector functions efficiently to ensure the growth of cancer cells." (PMID 30526672, 2018). "Tumor-induced CD4+ T cell anergy has been proposed as an immune evasion mechanism in cancer." (PMID 29844317, 2018). "CD4+ CAR T cells were co-cultured with either RMA or B16F10 tumor lines expressing B7H6." (PMID 29515240, 2018). "In addition, we further performed the percentage of CD4+CD25+FoxP3+ by flow cytometry to understand the molecular mechanisms of regulatory T cells for tumor growth." (PMID 29416605, 2018). "CD4+ T cells also induce more durable immune mediated tumor control than CD8+ T cells." (PMID 29732001, 2018). "As such, strategies to identify CD4+ T cells that can directly target tumor cells may focus on CD103+CD4+ T cells." (PMID 30505306, 2018). "This alteration in T cell regulators may alter CD4+ T cell subsets and disrupt the immune environment, promoting tumour growth, although further studies are required to confirm this." (PMID 30559928, 2018). "In addition, TGFβ can induce the differentiation of regulatory CD4+ T cells (Treg), an indicator of poor prognosis for many tumor types." (PMID 29721396, 2018). "Both CD8+ and CD4+ T-cell subsets are required for potent and sustained anti-tumor response." (PMID 29975720, 2018). "Although CTLs are recognized as the effector T cells in an anti-tumour response, CD4+ Th cells have a significant role in immunity against tumours, necessary for the activation of antigen specific effector cells and recruitment of cells of the innate immune system." (PMID 30200528, 2018). "Interestingly, most of the specific-neoantigen immune responses observed are mediated by CD4+ T cells and several studies highlighted a critical role for neoantigen-specific CD4+ T cell responses in tumor elimination." (PMID 30459932, 2018). "In addition, dCAR-modified CD4+ T cells also have cytotoxicity against cognate tumor cells (approximately 30%); therefore, CD4+ T cells possess lower target cell killing capacity compared with CD8+ T cells." (PMID 30103775, 2018). "However, there are two major T-cell subsets, including CD8+ cytotoxic T lymphocytes (CTL) and CD4+ regulatory T cells (Tregs), which play an opposite role in tumor immunity, respectively." (PMID 29967800, 2018). "Furthermore, depletion of Tregs using anti-CD25 antibodies augmented anti-tumor CD4+ and CD8+ T cell responses." (PMID 30854331, 2018). "Recent studies demonstrate that a subset of CD4+ T cells, referred to as CD4+CD25hi FoxP3+ naturally occurring Tregs, may accumulate in the tumor environment and suppress tumor-specific T-cell responses, thereby hindering tumor rejection." (PMID 30250191, 2018). "Despite these supportive roles, selectively modulating CD4+ populations could be used to elicit tumor shrinkage." (PMID 32914058, 2018). "For example, DC as the antigen-presenting cells (APC) is involved in the antitumor immune responses, while CD8+ T cell may dissolve and kill tumor cells, and CD4+ cell (including Foxp3+ Tregs) impose restrictions on tumor response." (PMID 29682534, 2018). "The ineffectiveness of the immune cell response mechanisms against tumour antigens may be in part due to the reduction in the number and activity of CD4+ T lymphocytes, also confirmed in our study, which impacts the function and activity of CD8+ T cells." (PMID 29490633, 2018). "Thus, the Tag7-activated CD3+CD4+ subpopulation of lymphocytes was only able to kill HLA-negative tumor cells, as has also been demonstrated for the cytokine IL-2-activated lymphocytes." (PMID 29850628, 2018).
tumor (continued). "Additionally, the level of CD3+CD4+FOXP3+ Treg cells in the tumor of PSPEI-PAA nanocomplex treatment group were declined compared to the PBS control group." (PMID 30960988, 2018). "The ability of these CD4+ CAR T cells to kill B7H6-expressing tumor cells was evaluated." (PMID 29515240, 2018). "One of major mechanisms that the CD8+ CTL inhibits tumor growth is by killing the tumor cells in a cytotoxic manner, while CD4+ Th1 cells may work by secreting cytokines." (PMID 29967800, 2018). "The most promising biomarker candidates in our example cohort comprise quantitative descriptions of co-localizations between CD8 and tumor cells (confirming previously known relevance) and the impact of CD4 cells on the anti-tumor immune response (pointing in a promising new research direction)." (PMID 30619761, 2018). "Recently, we reported intrahepatic CD4+ T cells are critical for anti-tumor surveillance in NAFLD." (PMID 29795111, 2018). "Additionally, it has been reported that the tumor microenvironment can favor the conversion of inducible Tregs from CD4+CD25−T cells, with the total pool of Tregs being comprised of both natural Tregs and induced peripheral Tregs." (PMID 30319662, 2018). "Dogs with CTLA-4 levels below the cutoff values, which were determined based on receiver operating characteristic curves, on peripheral CD4+, CD8+, and tumor infiltrating CD4+ lymphocytes had significantly longer survival than dogs with values above the cutoff." (PMID 30040869, 2018). "In both groups, high CD45, high CD4 count, high CD8 count, gender, receiving radiotherapy alone, TMZ therapy alone, salvage gamma knife (GKS) treatment, or tumor cells expressing IDH1 mutation, and MGMT methylation were all not significant prognostic factors under HR evaluation." (PMID 29910795, 2018). "Additionally, tumor microenvironment, being also inflammatory, contains substantial amount of TGF-β cytokine associated with ability to convert CD4+CD25− into CD4+CD25+FoxP3+ cells." (PMID 29785404, 2018). "Moreover, the peritumour CD3+ population was enriched in CD8+ cells, whereas CD4+ were found in the majority of CD3+ tumour cells." (PMID 30285662, 2018). "Moreover, tumor-infiltrating T-lymphocytes, including Tregs and few CD4+ and CD8+ T cells, also express PD1 at higher levels than that of the spleen populations." (PMID 29301364, 2018). "We then examined whether ablation of Eomes influences the numbers and effector function of CD4+ T cells in the tumor setting." (PMID 30619337, 2018). "Although not significant due to high animal to animal variation, a strong tendency toward an increased amount of CD4+FOXP3+ T cells expressing the CD8α activation marker was observed in the tumor when compared with circulating blood (mean values: 16.0 and 2.1%)." (PMID 29930558, 2018). "In addition, hypomethylation of signature effector CD4+ T cell loci were correlated with lower post-cystectomy tumour stage and overall better outcome, suggesting epigenetic staging of immune responses to be useful for clinical evaluation." (PMID 30075815, 2018). "Altogether, our data indicate that a non-secreted tumor Ag, that represents well most of the mutated proteins in cancer cells, is detected by tumor Ag-specific CD4+ T cells." (PMID 29844317, 2018). "Additionally, there was a significant increase in the CD8+ T cell population and reduction in CD4+ FOXP3+ Treg cells in the PSPEI-PAA nanocomplex treated mice tumor compared to PBS control mice tumor." (PMID 30960988, 2018). "In order to confirm that T cells are required for control of MIF KD tumors, we performed a T cell depletion experiment by treating WT and MIF KD 4T1 tumor-bearing mice with CD4 and CD8 depleting antibodies or isotype control antibodies (cIgG) throughout the course of tumor growth." (PMID 29864117, 2018). "However, the combination of SEP and αPD-L1 had synergistic effects in increasing the frequency of CD8+ and CD4+ T cells in spleen and tumor, ultimately inhibiting tumor growth." (PMID 29317734, 2018).
tumor (continued). "Furthermore,ST2L+CD4+CD25+ T cells also efficiently suppressedproduction of the proinflammatory cytokines IFN-γ by CD4+CD25− Tcells from tumor tissue, while ST2L−CD4+CD25+ T cells hadmilder suppressive function." (PMID 29950152, 2018). "The CD4+CD25+ Treg cell count is negatively correlated with tumor development and prognosis 8-12." (PMID 30517305, 2018). "However, evidence showed that the increase of CD4+ Tregs indicated poor prognosis in tumor-bearing individuals." (PMID 29967800, 2018). "In comparing the fold change of infiltration of immune cells based on EMT status, we observed an increased infiltration of cells with anti-tumor or immune stimulatory functions such as Th17, mature dendritic cells (mDC), and activated CD4 T-cells in ‘epithelial’ lung ADC." (PMID 29440769, 2018). "Tumor exome sequencing was performed in primary and metastatic lesions, CD4+ and CD8+ TIL, as well as PBMCs were analyzed for TCR composition by CDR3 length analysis and tested for recognition of individual tumor mutations (represented by synthetic peptides) by IFN-γ production." (PMID 30400835, 2018). "It is known that the CD4+CD25+ lymphocytes are often associated with the Treg subpopulation of cells, which are responsible for the suppression of the immune response in the organism that enables tumor cell survival." (PMID 29850628, 2018). "Furthermore, in the tumor draining lymph node we observed ibuprofen to reduce Rorgt+ CD4+ T cells and restore Granzyme B+ expression in T cells suppressed by the involution environment." (PMID 30285905, 2018). "Immune response requires CD4 for Ag recognition in cooperation with CD8 for tumor elimination." (PMID 30120362, 2018). "This review focuses on how the multilayered crosstalk between different Notches and NF-κB subunits may converge on Foxp3 gene regulation and orchestrate CD4+ regulatory T (Treg) cell function, particularly in a tumor microenvironment." (PMID 30364244, 2018). "SPs may also participate in tumour immunity, for example the presequence from midkine (a protein contributing to tumour progression) contains epitopes that are recognized by CD4+ T cells." (PMID 30469512, 2018). "Upon encountering their cognate antigen in a tumour setting, the pattern of their maturation and differentiation into separate CD4+ T cell lineages will be decided by the combined signals from the antigen-presenting cells, tumour cells and stroma cells present in this distinct environment." (PMID 30075815, 2018). "Autologous whole tumor antigens offer an unparalleled advantage as it allows DCs to process and present a broad range of TAAs to stimulate strong, polyclonal and long-term memory CD4+ and CD8+ T cell responses, potentially preventing tumor immune escape." (PMID 29600445, 2018). "The IgG2 isotype, often described as a poor mediator of ADCC since it only binds to activatory CD32a, efficiently depleted tumor-infiltrating Treg cells in vivo (Treg/total CD4+ T cells = 13%), with comparable activity to that observed in mice treated with the IgG1 and IgG1SDALIE isotype variants." (PMID 29576375, 2018). "We performed ICS assays to detect tumor-reactive CD4+ or CD8+ T cells." (PMID 29293510, 2018). "Some of the tumor infiltrating cells, e.g. CD4+, CD335+ cells were increased in the tumors of all responders mice, irrespective of which virus was employed, whereas CD8+, Foxp3+, CD141+ were increased and CD11b+ cells were decreased preferentially in R-115-treated mice." (PMID 30080893, 2018). "The combined action of induced cancer-specific CD8 and CD4 T-cells in the periphery by NCVs is likely to result in higher frequency of TILs in patients co-treated with ICI moving a “cold tumor” from the lower right quadrant to the upper right quadrat of “hot tumors”." (PMID 29678194, 2018).